FLNC (filamin C)
Diseases named in the same sentence as FLNC in open-access papers (continued):
Sharing a sentence is not in itself a finding about the gene and the disease.
tumor (17 papers, 2014 to 2025). "The underlying mechanism for the association of FLNC methylation and tumor cell differentiation requires further research." (PMID 26550574, 2015). "These evidences indicate that due to tumor heterogeneity, FLNC exhibits different roles through distinct regulatory mechanisms in various tumor types." (PMID 40672387, 2025). "Quantitative phosphoproteomics integrated with multiple bioinformatics analysis revealed a series of phosphopeptides and candidate proteins such as EEF2, U2AF2 and FLNC involved in tumor metastasis and invasion." (PMID 34437425, 2021). "It is necessary to study about these regulation of FLNC to elucidate its precise function in tumour progression." (PMID 30867563, 2019). "FLNC is an actin cross-linking cytoskeletal protein that contributes to the regulation of cell morphology, which can facilitate the metastasis of tumour cells." (PMID 30867563, 2019). "Subsequent analysis showed that the filamin C (FLNC) protein was significantly up-regulated in the tumor tissue compared with the adjacent non-tumor tissues and the expression level increased gradually with the tumor development." (PMID 27626164, 2016). "We provided evidence showing that filamin C inhibited the proliferation and the metastasis of tumor cells." (PMID 25577646, 2015). "Tissue expressions of FLNC (both in normal and tumor tissues) were examined by immunohistochemistry and quantitative RT-PCR analyses." (PMID 24946857, 2014). "Given FLNC’s similar actin-binding function, its dysregulation may likewise influence tumor cell invasion and metastasis." (PMID 41373405, 2025). "Functioning as actin-cross-linking protein, FLNC serves as a cytoskeleton protein to play a key role in providing mechanical strength and supporting cell morphology changes which can facilitate the metastasis of tumor cells." (PMID 27626164, 2016). "FLNC was identified as upregulated in iCCA relative to normal liver, suggesting a potential involvement in tumorigenesis and progression; subsequent studies confirmed its overexpression in CCA, associating it with adverse prognosis and modified tumor microenvironment attributes." (PMID 41373405, 2025). "The violin plot showed the metastasis-related genes were higher expression in LUAD tumor tissues, but only LAMC2, THBS2, ITGB4, COL1A1 and FLNC showed positively correlated with poorer survival of LUAD and the expression level of GPR115." (PMID 33330053, 2020). "In published studies, AGRN, ITGAV, FLNC, ILK, and RSU1 were overexpressed in HCC tumor tissues, thereby promoting tumor development, metastasis, and even leading to poor prognosis, which is consistent with our findings." (PMID 36110210, 2022). "However, the FLNC expression level in HCC and its roles in tumor cell invasion and metastasis are unclear." (PMID 27626164, 2016). "Upon immunohistochemical analysis of Ki67 and Filamin C expression in LNCaP tumors obtained from LNCaP tumor-bearing nude mice treated with two different concentrations of DU145 exosomes (10 μg and 100 μg), we confirmed that the expression of Filamin C had increased upon DU145 exosome treatment." (PMID 26840259, 2016). "Besides FLNC, ITGA2, COL1A1 and COL11A1 were tumor invasion and metastasis-related proteins." (PMID 27626164, 2016). "Interestingly, the role of FLNC, another member in the filament protein family, is not clear in tumor cell invasion and metastasis." (PMID 27626164, 2016).
cardiac disease (8 papers, 2017 to 2025). "Different genes have been found to be related to ALVC, and the more frequent are Desmoplakin (DSP), Filamin C (FLNC), Phospholamban (PLN), and Desmin (DES); however, there is a prevalence of variants of genes already known to be related to inherited cardiac disease and of gene-elusive cases." (PMID 35893404, 2022). "In addition, in patients with benign variants and patients without identified variants, testing a wider range of cardiac disease-related genes (such as FLNC, ALPK3, CDH, etc.)not included in our study would lead to greater utility of molecular analysis." (PMID 38254962, 2024). "Furthermore, mutations in non-desmosomal genes, including Transmembrane protein 43—luma (TMEM 43), Phospholamban (PLN), Filamin C (FLNC), Desmin (DES), and LMNA (Lamin A/C), have been identified as contributing to the pathogenesis of heart disease." (PMID 40361967, 2025). "Notably, truncating variants in genes such as TTN, FLNC, DSP, PKP2, and MYH7 were frequently reported, particularly in young decedents with no significant history of cardiac disease." (PMID 41374444, 2025).
infection (3 papers, 2021 to 2026). The state of being infected such as from the introduction of a foreign agent such as serum, vaccine, antigenic substance or organism. "Prior to infection, Filamin C was elevated by 4.3-fold in Pdpn-TG cells." (PMID 34707599, 2021).
prostate (1 paper, 2025). "Interestingly, MYLK, MYH11, and FLNC were identified as pivotal genes in studies of the immune microenvironment, and MYLK and FLNC were found to be associated with prostate pathogenesis and prognosis." (PMID 39762799, 2025).
urologic disease (1 paper, 2013). "In addition, meprin A and filamin C will require further studies in patients with renal or urologic disease or extreme dehydration, and development of their clinical-grade assays will require normalization for potential variations in total urine protein concentration." (PMID 23281308, 2013).
FLNC also shares sentences with these, for which no sentence is quoted: melanoma (3 papers); amyloidosis (2); bladder cancer (2); cardiovascular diseases (2); congenital myasthenic syndrome (2); glycogen storage disease (2); head and neck cancer (2); leukemia (2); limb-girdle muscular dystrophy (2); Long QT syndrome (2); Obesity (2); ventricular fibrillation (2); acute myocarditis (1); and glucocorticoid deficiency (1); anemia (1); arrhythmogenic right ventricular cardiomyopathy (1); arthrogryposis (1); asthma (1); atherosclerosis (1); axonal neuropathy (1); Barth syndrome (1); Brugada syndrome (1); Camptodactyly (1); cardiac arrhythmias (1); cardiofaciocutaneous syndrome (1); catecholaminergic polymorphic ventricular tachycardia (1); central nervous system disease (1); Chagas disease (1); cholangiocarcinoma (1); chronic atrophic gastritis (1).
A further 58 diseases each share a sentence with FLNC in 1 paper.